SOX3 (SRY-box transcription factor 3)
Diseases named in the same sentence as SOX3 in open-access papers (continued):
Sharing a sentence is not in itself a finding about the gene and the disease.
ovarian carcinoma (3 papers, 2017 to 2024). A malignant neoplasm originating from the surface ovarian epithelium. "Recent studies have reported that SOX3 is linked to various cancers, including esophageal squamous cell carcinoma, ovarian cancer, and T-cell lymphomas." (PMID 28335789, 2017). "Intriguingly, studies examining the response to chemotherapy drugs like cisplatin found that SOX3 expression was lower in tissues that were more resistant to the drug, suggesting a complex involvement of SOX3 in the progression of ovarian cancer." (PMID 38927713, 2024). "In ovarian cancer cells, upregulation of SOX3 was found to elevate cell proliferation rate, whereas inhibition reduced cell proliferation." (PMID 38927713, 2024). "Previous studies have reported that SOX3 is correlated with the development of several types of cancer, including esophageal squamous cell carcinoma, ovarian cancer, and T-cell lymphomas, and induces oncogenic transformation of chicken embryonic fibroblasts." (PMID 28335789, 2017). "Recent studies have reported that SOX3 is upregulated in cancer tissues and may therefore play an oncogenic role in esophageal squamous cell carcinoma, ovarian cancer, and T-cell lymphomas." (PMID 28335789, 2017). "This variability in SOX3 expression among human ovarian cancer cell lines highlights its differential behavior depending on the cell type, with metastatic cell lines showing increased SOX3 expression, potentially tying SOX3 to malignant transformations within ovarian tumors." (PMID 38927713, 2024). "SOX3 expression and localization in human ovarian cancer were detected mainly in cell nuclei, whereas normal ovarian tissue samples showed no SOX3 expression." (PMID 38927713, 2024). "Positive nuclear accumulation of SOX3 in immunohistochemistry staining was found in human ovarian cancer tissue samples, contrasting with the negative staining observed in control ovarian tissue." (PMID 38927713, 2024). "This body of research not only underscores the pivotal role of SOX3 in ovarian cancer but also connects it with other key molecular players like ALK, offering a better understanding of the molecular underpinnings of ovarian cancer and highlighting potential targets for therapeutic intervention." (PMID 38927713, 2024).
spina bifida (3 papers, 2020 to 2024). A congenital neural tube defect in which vertebrae are not fully formed. "In the Chinese family, the presence of spina bifida in the proband and scoliosis in 4 family members implicates a role for SOX3, which has been linked to neural tube defects in man, chicken, Drosophila and zebrafish." (PMID 31961795, 2020).
T-cell lymphomas (3 papers, 2011 to 2020). "Moreover, Sox3 was identified as a target of retroviral insertions causing T-cell lymphomas in mice and the Sox2 locus is frequently amplified in prostate cancer." (PMID 21483788, 2011). "SOX3 overexpression is involved in the pathogenesis of choriocarcinoma 28 and T cell lymphoma." (PMID 32363730, 2020).
cervical cancer (2 papers, 2023 to 2025). A primary or metastatic malignant neoplasm involving the cervix. "Of the three SOX genes found downregulated in Cluster 1, both SOX11 and SOX3 have been demonstrated to have oncogenic features in ovarian or cervical cancer." (PMID 37509311, 2023).
embryonal carcinoma (2 papers, 2014 to 2017). A non-seminomatous malignant germ cell tumor characterized by the presence of large germ cells with abundant cytoplasm resembling epithelial cells, geographic necrosis, high mitotic activity, and pseudoglandular and pseudopapillary structures formation. "Embryonal carcinoma cell line NT2/D1 provided us with a valuable model system to study the epigenetic state of SOX3 gene in pluripotent cells as well as in cells responding to neural differentiation-inducing stimuli." (PMID 28886103, 2017). "In the present study we have analyzed epigenetic modifications of the promoters of SOXB1 genes during early phases of retinoic acid (RA) induced neural differentiation of human embryonal carcinoma NTera2/D1 (NT2/D1) cells with a special focus on SOX3 gene." (PMID 28886103, 2017).
esophageal squamous cell carcinoma (2 papers, 2017 to 2024). Esophageal squamous cell carcinoma (ESCC) is a type of esophageal carcinoma (EC) that can affect any part of the esophagus, but is usually located in the upper or middle third. "In esophageal squamous cell carcinoma (ESCC), notable elevations in SOX3 expression were observed compared to non-neoplastic samples." (PMID 38927713, 2024).
hepatocellular carcinoma (2 papers, 2024 to 2025). A malignant tumor that arises from hepatocytes. "Additionally, SOX3 localization in the cytoplasm of hepatocellular carcinoma cells suggests it may have functions beyond those typically attributed to a nuclear transcription factor." (PMID 41012776, 2025).
laryngeal abductor paralysis (2 papers, 2022 to 2023). "We therefore hypothesize that altered regulation and ectopic expression of SOX3 caused by the identified complex interchromosomal insertion is the cause of X-linked congenital bilateral laryngeal abductor paralysis (Plott syndrome)." (PMID 35095096, 2022). "Further studies investigating the effect on SOX3 expression in neuronal tissue (iPS-induced) and molecular characterization of additional individuals with Plott syndrome would strengthen our assumption." (PMID 35095096, 2022). "Thus, SOX3 might also be an important regulator for the chemoreceptive pathway between the nucleus ambiguus, the carotid body and the posterior cricoarytenoid muscle, the perturbation of which is thought to be the cause of Plott syndrome." (PMID 35095096, 2022).
melanoma (2 papers, 2025). A malignant, usually aggressive tumor composed of atypical, neoplastic melanocytes. "Corroborating the correlation analyses, oral melanomas with positivity for SOX3 were more frequently associated with melanomas with a high proliferative index (p < 0.05)." (PMID 41012776, 2025). "In summary, low SOX3 expression was directly associated with increased cell proliferation in canine melanomas." (PMID 41012776, 2025). "In this sense, it is suggested that other molecular alterations may be similar between these species, such as the SOX3 protein mutation already observed in human melanomas." (PMID 41012776, 2025). "SOX3 is associated with tumor progression in liver cancer and ARHGEF9 promotes cytoskeleton variations that determine cell share in melanoma." (PMID 39416100, 2025). "Our data indicate that the cytoplasmic expression pattern of SOX3 in oral canine melanomas is similar to other described neoplasms." (PMID 41012776, 2025). "Due to its relationship with aggressiveness in different tumor types, we hypothesized that proteins SOX2, SOX3 and SOX10, in canine melanomas, play a role similar to that observed in human neoplasms." (PMID 41012776, 2025). "The cytoplasmic expression of SOX3 in oral canine melanomas had not been previously addressed in the literature." (PMID 41012776, 2025). "Although the expression of SOX2 is quite controversial, and the role of the SOX3 protein has not yet been elucidated, the SOX10 protein, another member of this family of transcription factors, has already been widely studied in melanomas." (PMID 41012776, 2025).
microcephaly (2 papers, 2023 to 2024). A congenital or acquired developmental disorder in which the circumference of the head is smaller than normal for the person's age and sex. "Since mutations in the closely related SoxB1 gene, Sox3, are associated with human syndromes that include microcephaly, the repression of these target genes might therefore also provide a link between loss of Sox3 activity and microcephaly." (PMID 38507426, 2024). "In this study, I will focus on two members of the SOXB1 group (SOX2 and SOX3) and two members of the SOXC group (SOX4 and SOX11) for their associations with microcephaly." (PMID 38094004, 2023).
small cell lung carcinoma (2 papers, 2007 to 2017). Small cell lung cancer (SCLC) is a highly aggressive malignant neoplasm, accounting for 10-15% of lung cancer cases, characterized byrapid growth, and early metastasis. "Previously, researchers have found that the transcription factor SOX3 of the SOX family was highly expressed in small cell lung cancer tissues." (PMID 29132362, 2017). "Thus, SOX1, SOX2, SOX3 and SOX21 as well as SOX4 were demonstrated to elicit humoral immune responses in small cell lung cancer patients." (PMID 17375044, 2007).
X-linked intellectual disability (2 papers, 2021 to 2022). An X-linked intellectual deficiency in which not enough information is known, reported or published to indicate whether a gene causes non-syndromic or syndromic presentations. "Duplications including SOX3 have been associated with variable clinical phenotypes, including X-linked intellectual disability (ID), GHD, X-linked hypopituitarism (XH), SRY-negative 46,XX disorders of sex development (DSD) and neural tube defects (NTD)." (PMID 33184694, 2021).
Anosmia (1 paper, 2021). An inability to perceive odors. "P/LP variants were detected in patients presenting with anosmia/hyposmia in genes previously reported for nIHH (GNRHR) or SOD/CPHD (LHX4, SOX3)." (PMID 34198905, 2021). "Perhaps a specific sort of defect in GNRHR, LHX4, or SOX3 can result in a complete clinical picture of Kallmann syndrome with smell disturbances." (PMID 34198905, 2021).
autism (1 paper, 2021). Persistent deficits in social interaction and communication and interaction as well as a markedly restricted repertoire of activity and interest as well as repetitive patterns of behavior. "Moreover, the candidate genes PAK3, OCRL, DCX, PTK2, KCNQ3, SOX3, and LAMA1 were associated with autism, brain disease, Dent disease, and other conditions that present ID as a hallmark, corroborating our findings." (PMID 33922640, 2021).
Autoimmunity (1 paper, 2022). The occurrence of an immune reaction against the organism's own cells or tissues. "The finding of autoreactivity of intergenic phage neighbor to SOX3 further supports the contention that autoimmunity-driven deregulation of multiple protein-coding and lncRNA genes is mechanistically involved in breast carcinogenesis." (PMID 37082114, 2022).
brain injuries (1 paper, 2021). "In turn, mutations of other transcription factors (e.g., PIT-1/POU1F1, PROP-1, LHX3, SOX2, SOX3, OTX2 and HESX1) lead to congenital MPHD, while hypothalamic-pituitary tumours (e.g., craniopharyngiomas), their treatment regimens or traumatic brain injuries result in acquired MPHD." (PMID 34445772, 2021).
chronic lymphocyte leukemia (1 paper, 2017). "Finally, hypermethylation of SOX3 was detected in chronic lymphocyte leukemia." (PMID 28886103, 2017).
congenital heart disease (1 paper, 2023). A heart disease that is present at birth. "This strengthens our belief that ROR2 regulates HSPA6 expression through the β‐catenin/SOX3 signalling pathway, providing some clinical implications for treating TOF in congenital heart disease." (PMID 37749917, 2023).
dilated cardiomyopathy (1 paper, 2017). Cardiomyopathy which is characterized by dilation and contractile dysfunction of the left and right ventricles. "The targets of the remaining MRs, e. g., SOX3 and POU3F3, were enriched for Dilated cardiomyopathy (P = 0.0308), Hedgehog signaling pathway (p = 0.0127), Intestinal immune network for IgA production (p = 0.0094), Axon guidance (p = 0.0389), and Vascular smooth muscle contraction (p = 0.0488)." (PMID 29101382, 2017).
esophageal cancer (1 paper, 2024). A primary or metastatic malignant neoplasm involving the esophagus. "This suggests that SOX3 holds promise as a valuable biomarker for prognostic prediction in esophageal cancer and a potential therapeutic target for ESCC." (PMID 38927713, 2024).
hemophilia B (1 paper, 2018). Hemophilia B is a form of hemophilia characterized by spontaneous or prolonged hemorrhages due to factor IX deficiency. "Our patient was diagnosed with mild hemophilia B after finding an 11 Mb deletion of Xq26.3q28 that included the following genes among others IDS,SOX3,FMR1,AFF2, and F9." (PMID 30264515, 2018).
Hydrocephalus (1 paper, 2012). Hydrocephalus is an active distension of the ventricular system of the brain resulting from inadequate passage of CSF from its point of production within the cerebral ventricles to its point of absorption into the systemic circulation. "This study provides further evidence that SCO function is essential for the prevention of hydrocephalus and indicates that overexpression of Sox3 in the dorsal midline alters progenitor cell differentiation in a dose-dependent manner." (PMID 22291885, 2012). "Due to the non-communicating nature of the hydrocephalus phenotype in the Sox3 transgenic model and the retention of CSF within the rostral ventricles of the brain, it is unlikely that the ChP from the fourth ventricle is contributing to the CH phenotype." (PMID 22291885, 2012).
neuroblastoma (1 paper, 2023). Neuroblastoma (NB) is the most common solid, extracranial childhood tumor. "Similarly, in the neural crest derived tumor, neuroblastoma, ADAM11 expression is higher than in the normal tissue, with a concurrent increase in Smad1-5 expression and decreases in Sox3 expression." (PMID 37766964, 2023).
pituitary (1 paper, 2021). "A hemizygous SOX3 allelic variant (p.Met304Ile) was found in a male patient with IGHD and hypoplastic anterior pituitary." (PMID 34440302, 2021).
Retinal dystrophy (1 paper, 2025). Retinal dystrophy is an abnormality of the retina associated with a hereditary process. "Transcriptomics showed extremely low expression of SOX3 in our control and retinal dystrophy ROs, with small but significant differences in expression only in IRDF-1." (PMID 39892393, 2025). "The low level of expression combined with the absence of any retinal dystrophy associated with SOX3 deficiency suggested it was also unlikely to be the cause of IRD." (PMID 39892393, 2025). "However, if CDR1as/ciRS-7 transcription originates solely from the LINC00632 promoter within the SOX3 TAD, then we would expect it to be upregulated in our retinal dystrophy RO models, owing to the upregulation of the parental linear isoforms." (PMID 39892393, 2025). "However, our retinal dystrophy families showed no congenital abnormality and no clinical features consistent with SOX3 dysregulation." (PMID 39892393, 2025).
X-linked hypoparathyroidism (1 paper, 2020).
tumor (18 papers, 2011 to 2026). "In these contexts, SOX3 dysregulation is implicated in tumor development and progression, potentially via its influence on apoptosis, migration and proliferation." (PMID 41268614, 2026). "This increased SOX3 expression in GC is intricately linked to differentiation, lymph node metastasis, and tumor invasion." (PMID 38927713, 2024). "The correlation between SOX3 expression and clinicopathological features further indicated that high SOX3 expression was linked to lower tumor capsule formation, poorer tumor differentiation grades, and worse TNM classification." (PMID 38927713, 2024). "Elevated SOX3 expression was associated with advanced tumor progression and worse prognosis in HCC patients." (PMID 38927713, 2024). "These SOX3-positive cells are associated with an indolent tumor phenotype observed in PDC and GBM tissue samples." (PMID 37894405, 2023). "We found that the serum SOX3 levels were remarkably associated with tumour differentiation (P < .001), lymph node metastasis (P = .002), primary tumour invasion (P = .027) and pTNM stage (P < .001)." (PMID 32363730, 2020). "In human neoplasms, SOX3 expression has been linked to poorer prognosis." (PMID 41012776, 2025). "SOX3 can be regulated by different transcription factors, including ERK, causing neoplastic cells to play crucial roles in tumor progression, leading the tumor to a more aggressive phenotype." (PMID 41012776, 2025). "Immunohistochemical analysis of clinical samples confirmed the presence of SOX3 in the nucleus of all analyzed tumor samples, revealing elevated SOX3 expression in GBM samples compared to non-tumoral brain tissues." (PMID 38927713, 2024). "Collectively, these observations suggest that SOX3 plays a role in invasion and migration depending on tumor subtype and spatial distribution." (PMID 38927713, 2024). "SOX3 exhibits varied expression patterns correlated with clinicopathological parameters in diverse tumor types." (PMID 38927713, 2024). "This review will discuss the involvement of SOX3 in multiple human neoplasms and present the SOX3 clinical correlation in concert with tumor behavior." (PMID 38927713, 2024). "Our objective is to shed light on the role of SOX3 in tumorigenesis by examining gene and protein expression patterns in clinical specimens and in vitro and in vivo models across various tumor types." (PMID 38927713, 2024). "The immunolocalization of SOX3 by IHC demonstrated that SOX3 was predominantly localized in the nucleus of tumor cells, aligning with its expected role as a TF." (PMID 38927713, 2024). "CELF2 shapes a H3K9me3-repressive landscape in the SOX3 gene, thereby promoting a proliferating tumor cell phenotype." (PMID 37894405, 2023). "The downregulation of SOX2 and SOX3 to influence tumour cell invasion was examined with Transwell invasion assays." (PMID 34953010, 2022). "The downregulation of SOX2 and SOX3 to influence tumour cell migration was evaluated using wound‐healing migration assay." (PMID 34953010, 2022). "The SOX3 levels in tumour tissues were remarkably correlated with primary tumour invasion (T1/2 vs T3/4, P = .041) and patient ages (P = .027)." (PMID 32363730, 2020). "SOX3 levels in cancer tissues were remarkably related to tumour differentiation, lymph node metastasis, primary tumour invasion and pTNM (pathological TNM) stage." (PMID 32363730, 2020). "Stratified analyses indicated that the SOX3 levels in tumour tissues were correlated with the OSs in both patients of pTNM stage I/II (P = .016) and stage III/IV (P = .015) conversely." (PMID 32363730, 2020). "We first determined the SOX3 mRNA and protein levels in 42 cases of human OS tissues and in adjacent non-tumor samples by qRT-PCR and Western blot analysis." (PMID 28335789, 2017). "Epithelial tumor cells express high levels of Sox3 and low levels of Snail1, and the opposite is true for mesenchymal tumor cells." (PMID 21920318, 2011).